AOC1 (amine oxidase copper containing 1)
Description:
Catalyzes the oxidative deamination of primary amines to the corresponding aldehydes with the concomitant production of hydrogen peroxide and ammonia. Its preferred substrates are the diamines histamine and 1-methylhistamine and it could therefore play a role in allergic and immune responses. Has a broad specificity for diamines and can also act on cadaverine and putrescine, two products of amino acid catabolism. It could also act on polyamines, like spermidine and spermine though less efficiently, and regulate various biological processes.
Synonyms: KAO; KDAO; ABP; ABP1; DAO; DAO1
Tractability: Small molecule: an approved drug acts on it; a structure with a bound ligand is known; a high-quality ligand is known; it has a high-quality binding pocket; it belongs to a druggable protein family. Antibody: UniProt places it where antibodies can reach, with high confidence; its Gene Ontology location is reachable by antibodies, with high confidence; UniProt predicts a signal peptide or a membrane-spanning region. PROTAC: ubiquitination databases record sites on it; a small molecule that binds it is known.
Target class: Enzyme; Oxidoreductase
Chemical probes: DIMINAZENE
Gene: Protein-coding gene on chromosome 7 (150,824,627 to 150,861,504, forward strand). Ensembl gene ENSG00000002726.
Subcellular location: Secreted, extracellular space; Cell membrane
Pathways (Reactome):
Metabolism: Histidine catabolism; Phase I - Functionalization of compounds
Immune System: Neutrophil degranulation
Gene Ontology:
Molecular function: calcium ion binding; copper ion binding; diamine oxidase activity; heparin binding; histamine oxidase activity; primary methylamine oxidase activity; protein binding; protein homodimerization activity; putrescine oxidase activity; quinone binding
Biological process: putrescine metabolic process; amine metabolic process
Cellular component: extracellular exosome; extracellular region; plasma membrane; bicellular tight junction; peroxisome; specific granule lumen
Genetic constraint (gnomAD): Loss-of-function variants: 58 observed, 57.62 expected, observed/expected ratio (o/e) 1.01, 90% interval 0.81 to 1.25. The upper end of that interval is the gene's LOEUF score, 1.25, which puts it in group 5 of 6, group 1 being the genes least tolerant of losing a copy. Missense variants: 917 observed, 1,032.2 expected, observed/expected ratio (o/e) 0.89, 90% interval 0.84 to 0.94. Synonymous variants: 401 observed, 434.1 expected, observed/expected ratio (o/e) 0.92, 90% interval 0.85 to 1.
Homologues: Orthologues: chimpanzee AOC1 (99% identical), macaque AOC1 (95% identical), rabbit AOC1 (86% identical), pig AOC1 (82% identical), rat Aoc1 (81% identical), mouse Aoc1 (80% identical), guinea pig AOC1 (80% identical), mouse Aoc1l3 (58% identical), mouse Aoc1l1 (58% identical), rat Svs1 (58% identical), rat Doxl2 (58% identical), mouse Aoc1l2 (56% identical), and 3 more. Paralogues in human: AOC2 (40% identical), AOC3 (38% identical).
Diseases named in the same sentence as AOC1 in open-access papers:
AOC1 is named in the same sentence as 89 diseases in open-access papers, as found by Europe PMC text mining. Sharing a sentence is not in itself a finding about the gene and the disease. The quoted sentences say what the papers report.
gastric cancer (9 papers, 2020 to 2025). A primary or metastatic malignant neoplasm involving the stomach. "Meanwhile, AOC1 has been documented as an oncogene in gastric cancer through activating the AKT signaling pathway." (PMID 38956710, 2024). "In gastric cancer and hepatocellular carcinoma, AOC1 functions as an oncogene, either by activating the AKT signaling pathway and EMT or by regulating the IL-6/JAK/STAT3 pathway." (PMID 37525249, 2023). "Previous studies revealed that AOC1 played a vital role in gastric cancer and colorectal cancer progression." (PMID 37257820, 2023). "Although previous reports revealed that AOC1 affected the occurrence and development of gastric cancer and Wilms tumors, its role in colorectal cancer has not been elucidated." (PMID 34026633, 2021). "Recently, a study revealed that AOC1 promoted the progression of gastric cancer, and another study has shown that AOC1 was a downstream target gene of the Wilms tumor protein that affected kidney development." (PMID 34026633, 2021). "AOC1 knockdown in gastric cancer cells could suppress the propagation, invasiveness and migration, induce activation of the caspase cascade, and inactivated AKT signaling pathway." (PMID 36788514, 2023).
colorectal cancer (8 papers, 2015 to 2025). A primary or metastatic malignant neoplasm that affects the colon or rectum. "The positive expression of AOC1 was significantly associated with poor clinical outcomes of colorectal cancer and promoted the tumor cell invasion phenotype by inducing the epithelial-mesenchymal transition (EMT) pathway." (PMID 40813717, 2025). "For example, positive expression of AOC1 was significantly associated with worse clinical outcomes in colorectal cancer and accelerated tumor cell aggressive phenotypes via inducing EMT pathway." (PMID 38956710, 2024). "In the current study, we detected the expression of AOC1 in CRC tissues and found that AOC1 expression was significantly increased in human colorectal cancer tissues compared to normal tissues." (PMID 34026633, 2021). "Another copper-dependent enzyme called AOC1 has been shown to promote the proliferation and migration of colorectal cancer cells in both in vivo and in vitro experiments, exhibiting a significant correlation with unfavorable clinical outcomes among colorectal cancer patients." (PMID 39691393, 2024). "In addition, AOC1 was also found promoting cancer progression in gastric and colorectal cancer by activating AKT pathway and epithelial–mesenchymal transition process." (PMID 37257820, 2023). "Furthermore, AOC1 has been demonstrated to promote gastric and colorectal cancer, although, little is known about its role in other cancers." (PMID 35922412, 2022). "In the next study, We will compare the specificity and sensitivity of AOC1 and CEA to analyze whether AOC1 can replace or be used in combination with CEA to predict colorectal cancer and its prognosis clinically." (PMID 34026633, 2021). "We observed that AOC1 expression was noticeably higher in CRC liver metastatic tissues than in primary tumor tissues by IHC and qRT-PCR, and significant associated with liver metastasis (p < 0.001), indicating that AOC1 is a potential biomarker for predicting liver metastasis of colorectal cancer." (PMID 34026633, 2021). "In colorectal cancer (CRC) tissues, AOC1 levels were promoted, and the functional experiments demonstrated that AOC1 silence retarded the migration and proliferation of CRC cells." (PMID 40813717, 2025). "AOC1 can promote epithelial–mesenchymal transition via the AKT pathway in digestive system malignancies (gastric and colorectal cancer), thereby promoting tumor progression." (PMID 35922412, 2022). "Amine oxidase copper containing 1 (AOC1) is a gene whose biological function in colorectal cancer (CRC) has not been elucidated." (PMID 34026633, 2021).
prostate carcinoma (6 papers, 2022 to 2024). A carcinoma that arises from epithelial cells of the prostate gland. "Conversely, high expression of AOC1 is significantly associated with reduced proliferation and migration in prostate cancer both in vitro and in vivo." (PMID 35922412, 2022). "Because it is known that AOC1 has relatively low expression in prostate cancer, whether AOC1 is associated with a poor prognosis for patients has attracted our attention." (PMID 35922412, 2022). "SOX15 transcription enhances the function of AOC1 to modulate ferroptosis and the progression of prostate cancer." (PMID 38164286, 2024). "To confirm our results, we knocked down AOC1 in LNCaP and PC-3, which resulted in a significant increase in the malignant behaviors of prostate cancer cells after AOC1 is knocked down." (PMID 35922412, 2022). "Consistent with clinical results, overexpression of AOC1 is remarkably able to inhibit the growth of 22Rv1 and DU145 prostate cancer cells; however, the escalation of AOC1 significantly decreased the EdU level in both 22Rv1 and DU145 cells." (PMID 35922412, 2022). "Downregulation of PAH and AOC1 and upregulation of DDC, LIN01436, and ORM1 were associated with the development of prostate cancer." (PMID 36497304, 2022). "Three genes (CD177, DUOX1, and AOC1) were downregulated in prostate cancer through the analysis of bioinformatics data; the roles of both CD177 and DUOX1 in prostate cancer have been reported." (PMID 35922412, 2022). "Consistent with previous results, TCGA data also proved that AOC1 expression is reduced in prostate cancer; this was also shown by the GEO dataset results." (PMID 35922412, 2022). "To demonstrate the role of AOC1 in the cell biology of prostate cancer, we overexpressed AOC1 in prostate cancer cell lines 22Rv1 and DU145." (PMID 35922412, 2022). "The results showed that the mRNA expression of AOC1 in prostate cancer was lower than that in normal tissues." (PMID 35922412, 2022). "Abatement of AOC1 in prostate cancer tissue is positively correlated with the tumor size, lymph node metastasis, and Gleason score for prostate cancer." (PMID 35922412, 2022). "The sensitivity of prostate cancer cells to ferroptosis inducers, such as ML210, was surprisingly reduced after AOC1 overexpression, which means that AOC1 may affect ferroptosis in prostate cancer cells." (PMID 35922412, 2022). "The roles of CD177 and DUOX1 in prostate cancer have been comprehensively reported; however, how AOC1 is involved in prostate cancer remains unclear." (PMID 35922412, 2022). "In the present study, we demonstrated that SOX15 positively regulates AOC1 expression and that AOC1 has a tumor suppressor function in prostate cancer by downregulating the proliferation and migration of prostate cancer cells via the decomposition of spermidine." (PMID 35922412, 2022). "However, WT1 expression is significantly increased in prostate cancer but is poorly correlated with AOC1 in prostate cancer, which makes it difficult to explain why AOC1 expression is significantly depleted in prostate cancer." (PMID 35922412, 2022). "In summary, AOC1 depletion was able to accelerate the progression of prostate cancer cells, which was inhibited after simultaneously overexpressing SOX15, further demonstrating the mechanism of action of the SOX15/AOC1/ferroptosis axis in the modulation of prostate cancer development." (PMID 35922412, 2022). "In previous studies, transcription factor WT1 was shown to regulate AOC1 expression; however, its association with AOC1 in prostate cancer is not strong." (PMID 35922412, 2022). "Similarly, the MDA and Liperfluo assays verified that simultaneous supplementation of spermidine and AOC1 can easily cause lipid peroxidation in both 22Rv1 and DU145 prostate cancer cell lines." (PMID 35922412, 2022). "It is known that AOC1 and spermidine can suppress prostate cancer proliferation, but the mechanism remains unclear." (PMID 35922412, 2022).
prostate carcinoma (continued). "Here, we reveal a novel action of AOC1 and a tumor suppressor mechanism in prostate cancer." (PMID 35922412, 2022). "The results showed that only the expression of SOX15 in prostate cancer was consistent with AOC1." (PMID 35922412, 2022). "However, AOC1 promotes ferroptosis and inhibits prostate cancer progression." (PMID 37525249, 2023). "Therefore, there must be another mechanism that regulates AOC1 expression in prostate cancer." (PMID 35922412, 2022). "This study innovatively demonstrates that the transcription factor SOX15 can positively regulate AOC1 expression in prostate cancer, whereas ROS generated by the breakdown of spermidine by AOC1 can promote ferroptosis, thus playing an important role in inhibiting prostate cancer progression." (PMID 35922412, 2022). "In prostate cancer, SOX15 functions as a tumor suppressor by upregulating AOC1, which reduces the proliferation and migration of prostate cancer through the activation of reactive oxygen species and ferroptosis." (PMID 38331879, 2024). "We confirmed that supplementation of AOC1 expression was able to inhibit the proliferation and migration of prostate cancer cell lines (22Rv1 and DU145), suggesting that AOC1 acts as a prostate cancer tumor suppressor gene." (PMID 35922412, 2022). "Thus, the SOX15/AOC1/ROS axis might be a promising therapeutic target for prostate cancer." (PMID 35922412, 2022). "To date, AOC1 has been reported to promote the epithelial-mesenchymal transition (EMT) in gastric glandular cells and gastric carcinogenesis, and to inhibit cancer cell proliferation in prostate cancer." (PMID 37854606, 2023). "Nevertheless, there have been no investigations of AOC1 and its regulatory mechanism in prostate cancer." (PMID 35922412, 2022). "Although the effect of AOC1 on kidney development via WT1 has been reported, its role in prostate cancer remains unknown, but of great interest." (PMID 35922412, 2022). "Targeting AOC1 and SOX15 may be promising for the treatment of prostate cancer." (PMID 35922412, 2022).
fibromyalgia (5 papers, 2023 to 2025). A chronic disorder of unknown etiology characterized by pain, stiffness, and tenderness in the muscles of neck, shoulders, back, hips, arms, and legs. "HIT and DAO deficiency are associated with fibromyalgia, particularly in women with AOC1 (amine oxidase, copper containing 1, which codifies the DAO enzyme) gene variants, which are associated with a reduced DAO enzyme activity." (PMID 38337486, 2024). "This study constitutes the first step in the search for AOC1 gene variants associated with fibromyalgia symptoms and low DAO enzyme activity." (PMID 37359379, 2023). "This study addressed the combined effect of four AOC1 gene variants, rs10156191, rs1049742, rs1049793, and rs2052129, on fibromyalgia, measured using the FIQ, sleep quality, atopic dermatitis, migraine, GI disorders, allergies, and intolerances in adult women." (PMID 37359379, 2023). "The AOC1 gene variants associated with low enzyme activity may be associated with fibromyalgia symptoms, like many neurological or digestive disorders." (PMID 36979637, 2023). "Variants of the AOC1 gene that are associated with genetic DAO deficiency could serve as a disruptive biomarker in patients with fibromyalgia." (PMID 36979637, 2023). "However, in other studies in subjects with migraines, fibromyalgia, insomnia-related symptoms, histamine intolerance, ADHD, and LUTS in which the prevalence of AOC1 gene variants was determined, serum levels of DAO enzyme were not measured." (PMID 40004469, 2025). "Variants of AOC1 are associated with reduced DAO activity, resulting in accumulation of high levels of histamine and causing a wide range of neurological, gastrointestinal, and epidermal disorders, which are present in people with fibromyalgia." (PMID 37359379, 2023). "However, several diseases and symptoms have not been approached from a genetic perspective, much less by combining variants of the AOC1 gene associated with low DAO activity, to observe the predisposition to develop certain pathologies, such as fibromyalgia, when risk alleles accumulate." (PMID 37359379, 2023).
insomnia (5 papers, 2023 to 2026). A sleep disorder characterized by difficulty in falling asleep and/or remaining asleep. "This exploratory study was designed to assess the effect of a diamine oxidase (DAO) enzyme supplement on insomnia symptoms in patients with alterations of the AOC1 gene, which encodes the DAO enzyme." (PMID 41437955, 2026). "In this exploratory study, the use of a DAO supplement for 28 days improved insomnia symptoms in the presence of genetic variants of the AOC1 gene and showed a synergy with melatonin." (PMID 41437955, 2026). "This exploratory study shows that in patients with insomnia-related symptoms and SPNs of the AOC1 gene, which encodes the DAO enzyme, the administration of a dietary DAO supplement for 28 days was associated with improvement of sleep symptoms." (PMID 41437955, 2026). "Cumulative effect of the AOC1 gene variants rs10156191, rs1049742, rs1049793, and rs2052129 on the presence of insomnia, atopic dermatitis, migraines, GI disorders, allergies, and intolerances." (PMID 37359379, 2023). "Interestingly, a recent study carried out in a sample of 167 adult patients with symptoms of insomnia who underwent genotyping analysis of the four most relevant SNP variants of the AOC1 gene, DAO enzyme deficiency was present in 138 patients, with a prevalence rate of 82.6 % (95 % CI 76–88.1 %)." (PMID 41437955, 2026). "However, based on the high frequency of the allele frequencies found in patients with insomnia-related symptoms, the genotyping assessment of the AOC1 gene may constitute a valuable biomarker of DAO enzymatic activity in subjects presenting with sleep problems." (PMID 39200725, 2024). "In a consecutive clinical sample of 167 adults presenting with typical nighttime and daytime insomnia-related symptoms, the prevalence of genetic DAO deficiency based on the analysis of the four most relevant SNP variants of the AOC1 gene was 82.6%." (PMID 39200725, 2024). "This study shows that dietary supplementation with DAO may be a clinically relevant approach for improving insomnia symptoms in patients with genetic anomalies of the AOC1 gene." (PMID 41437955, 2026). "Likewise, the presence of some clinical manifestations in patients with insomnia were independent predictors of SNPs of the AOC1 gene." (PMID 39200725, 2024). "Therefore, it was hypothesized that DAO dietary supplementation may be a useful strategy for improving sleep problems in patients with insomnia symptoms who were carriers of SNPs of the AOC1 gene." (PMID 41437955, 2026).
migraines (5 papers, 2023 to 2025). "Cumulative effect of AOC1 gene variants rs10156191, rs1049742, rs1049793, and rs2052129 on intensity of symptoms related to quality of sleep, atopic dermatitis, migraines, and GI disorders." (PMID 37359379, 2023). "In another study conducted in Spain with 197 patients with migraine and 245 healthy controls, AOC1 SNP rs10156191, which is linked to decreased DAO enzyme activity, was found to be associated with the risk of developing migraine, especially in women." (PMID 36979637, 2023).
ulcerative colitis (4 papers, 2021 to 2024). An inflammatory bowel disease involving the mucosal surface of the large intestine and rectum. "The AOC1 is an important target for the treatment of autoimmune and inflammatory diseases due to its role in immune cell migration, e.g., for the intervention of ulcerative colitis." (PMID 38998524, 2024).
ischemia (3 papers, 2024 to 2025). A hypoperfusion of the BLOOD through an organ or tissue caused by a PATHOLOGIC CONSTRICTION or obstruction of its BLOOD VESSELS, or an absence of BLOOD CIRCULATION. "AOC1 gene encodes diamine oxidase, and human AOC1 is thought to have in vivo functions in cell proliferation, inflammation, allergic reactions, and ischemia." (PMID 40343124, 2025).
atopic dermatitis (2 papers, 2009 to 2023). "In the first case, women with a higher number of risk alleles had a higher intensity of dry skin, typical of atopic dermatitis, than the group with only two risk alleles of the AOC1 gene." (PMID 37359379, 2023).
glioma (2 papers, 2022 to 2025). A benign or malignant brain and spinal cord tumor that arises from glial cells (astrocytes, oligodendrocytes, ependymal cells). "However, the effect of AOC1 on glioma progression remains unclear." (PMID 40761256, 2025).
hepatocellular carcinoma (2 papers, 2023 to 2025). A malignant tumor that arises from hepatocytes. "AOC1 promoted malignant features of hepatocellular carcinoma (HCC) cells, including proliferation, migration, and invasion." (PMID 40813717, 2025).